IL7 (interleukin 7)
Diseases named in the same sentence as IL7 in open-access papers (continued):
Sharing a sentence is not in itself a finding about the gene and the disease.
tumor (continued). "This led us to consider instead whether the increased fraction of CD8+ TCM in tumor for the IL-7–ALT group simply reflected the composition of the preadministration product." (PMID 40244705, 2025). "To assess the potential of C8A8 in enhancing the anti-tumor activity of IL-7-CAR-T cells, we conducted co-culture experiments with various tumor cell lines, including HCC827, H23, and K562, at different effector-to-target (E:T) ratios in the presence of 30 μg/mL C8A8." (PMID 41450878, 2025). "In another such study, syngeneic tumor models were treated with a pool of IL7, IL12 and IFNα." (PMID 40321762, 2025). "Thus, while IL-15 is an appealing cytokine for amplifying immediate cytotoxic potential, IL-7 has better tolerability and exerts broader, more durable effects that favor long-term immune persistence and tumor control." (PMID 41550947, 2025). "Notably, IL-7-CAR-T cells were able to clear the tumor in 14 days, which was faster than the CAR-T cells." (PMID 41450878, 2025). "Furthermore, engineering CAR-T cells to express membrane-bound IL-7 has emerged as a promising strategy to enhance their in vivo persistence and anti-tumor efficacy." (PMID 41450878, 2025). "Furthermore, to evaluate the in vivo anti-tumor activity of IL-7-CAR-T cells, we generated xenograft tumor-bearing mice by subcutaneously injecting HCC827/Luc cells into 7-week-old male NPG mice." (PMID 41450878, 2025). "This indicated that exogenous IL-7 could enhance the ability of WT tumor cells to induce the immunosuppressive state of macrophages, and this phenomenon was validated in the human OVCAR3/THP-1 co-culture model." (PMID 41360767, 2025). "In contrast, the approach we explored has the benefit of being “self-regulating” while efficiently delivering cytokine at the tumor site as – (i) IL-7 production is dependent on antigenic stimulation of C.P7 T cells, and this (ii) allows tumor localized C.M7R cells to benefit." (PMID 40808942, 2025). "Additionally, the human–mouse chimeric antibody C8A8, derived from m8A8, was found to significantly amplify the anti-tumor activity of IL-7-engineered CAR-T cells." (PMID 41450878, 2025). "Additionally, replacing IL-2 with IL-7 and IL-15 in the culture media showed beneficial effects for the long-term survival and anti-tumor function of UCAR-T cells." (PMID 39906740, 2024). "IL-7 stimulates anti-tumor responses such as autophagy, migration, proliferation, and angiogenesis." (PMID 39309012, 2024). "In addition, expression of IL-7 in the patient’s tumor tissue and expression of the IL-7 receptor in T cells were higher than those of the control group, suggesting a T-cell-mediated immune response within the TME." (PMID 39093440, 2024). "Furthermore, IL-7 administration led to a delayed tumour growth and increased survival compared to control." (PMID 39315059, 2024). "Subsequently, we hypothesized that adding CD25 depletion to our IL7 agonist would further dampen tumor growth, which indeed was observed." (PMID 38554147, 2024). "Whether used as monotherapy or in combination with tumour vaccines, oncolytic viruses, or CAR T cell therapy, IL-7 enhances T cell infiltration, thereby improving anti-tumour efficacy." (PMID 38675377, 2024). "Moreover, the cytokine IL-7 promotes the differentiation of CD4+ T cells into Th9 cells with enhanced anti-tumour activity." (PMID 38675377, 2024). "Exogenous IL-7 administration has also been shown to recover circulating lymphocyte counts as well as T cell tumour infiltration in a mouse model of hepatocellular carcinoma after tumour-bearing hind leg irradiation." (PMID 39315059, 2024). "In addition to directly acting on the tumor, IL7 exerts effects on lymphopoiesis by stimulating T-cell precursor development in the bone marrow." (PMID 38554147, 2024).
tumor (continued). "In addition, IL-7 can also down-regulate the expression of tumour growth factor-β and inhibit immunosuppression to promote anti-tumour efficacy, suggesting potential clinical applications for anti-tumour immunotherapy." (PMID 38675377, 2024). "We found that IL7/CCL19-producing CAR-T cells generated from the patient’s PBMC showed potent therapeutic effects against the solid cancer model established by inoculating organoids from the autologous tumor tissue." (PMID 39240078, 2024). "IL-7 is mainly known for its anti-tumor effects mediated by immune-driven tumor eradication." (PMID 38835768, 2024). "IL-7 also enhances anti-tumour immune responses by counteracting immunosuppressive mechanisms." (PMID 38675377, 2024). "P1A tumor antigen-specific TCR-T cells which produced IL7/CCL19, showed noticeably increased anticancer effects and produced long-term memory responses by enhancing the infiltration of dendritic cells and T cells in tumor tissues, including both endogenous T cells and transplanted P1A T cells." (PMID 38693513, 2024). "IL-7 adjuvants also help to prolong the survival of activated T cells, enhance effector responses, and increase cytokine production, thereby improving the immune effect of tumour vaccines." (PMID 38675377, 2024). "The combination of IL-12 and IL-7 may exert a long-term anti-tumor effect and it is a potential combination strategy to fulfil the anti-tumor effect of IL-12 effectively." (PMID 38753073, 2024). "Conversely, B7–H3 CAR-T and B7–H3 CAR-T/IL-7 cells showed better anti-tumor persistence." (PMID 39093440, 2024). "Notably, IL-7 can improve the tumour microenvironment by promoting the development of Th17 cells, which can in turn promote the recruitment of effector T cells and NK cells." (PMID 38675377, 2024). "Furthermore, IL-7 has been shown to have anti-tumour effects in T cell receptor (TCR-T) cells, in addition to its known impact on CAR-T calls." (PMID 38675377, 2024). "IL-7 can also be used as an adjuvant in combination with tumour vaccine therapy to increase T lymphocyte infiltration into the tumour microenvironment, thereby enhancing the anti-tumour effect of cancer vaccines." (PMID 38675377, 2024). "Hence, expression of IL-7 in oncolytic viruses shows great potential to induce anti-tumor effects individually and in combination with ICI therapy and chemotherapy." (PMID 39309012, 2024). "Early results from this trial suggest that IL-7 gene therapy may enhance anti-tumour immune responses and improve clinical outcomes in such patients." (PMID 38675377, 2024). "Similarly, when incubated with UCH2 cells, B7–H3 CAR-T/IL-7 cells significantly enhanced tumor-killing activity and promoted the release of pro-inflammatory cytokines." (PMID 39093440, 2024). "In addition, we show as an adjuvant, dex in combination with CAR T cells and IL-7 led to long-term tumor control." (PMID 38140726, 2024). "Additionally, the increased levels of anti-tumor interleukins IL-4, IL-7, IL-28a, and IL-33 in miR-29 overexpressing tumors suggest a role for these microRNAs in bolstering anti-tumor immunity." (PMID 38890285, 2024). "Indeed, tumor-T (C1), APC-T (C8), and tumor-monocyte (C4) colocalization was enhanced in the control or rIL7 samples as predicted (C1, control-enriched; C4 and C8, IL-7-enriched)." (PMID 38424167, 2024). "Furthermore, the increase in IL-7 with AuNP-P3 can enhance T-cell activity, improving tumour radiosensitivity by boosting immune responses against cancer cells." (PMID 39682192, 2024). "The findings above suggest that combining CAR T cell therapy with IL-7 expression could have a positive anti-tumour immune effect, making it a promising option for clinical use." (PMID 38675377, 2024). "Moreover, mice with complete tumor elimination were able to resist reactivation of the same tumor cells, suggesting that mice treated with the combination of IL-7 and IL-12 developed long-term tumor-specific immune memory." (PMID 38753073, 2024).
tumor (continued). "As IL7 was linked to improved patient outcomes and T-cell memory development, we hypothesized that the addition of IL7 into the TME would result in reduced tumor growth, which was studied using mouse orthotopic HNSCC models." (PMID 38554147, 2024). "In addition, IL-7 can amplify initial T cells and anti-tumor activity with minimal side effects and good patient tolerance, providing an opportunity to use of IL-7 in tumor therapy." (PMID 39093440, 2024). "Such tumor-induced remodeling of FRCs, in particular, reduced CCL21 expression, is associated with perturbed lymphocyte compartmentalization and proliferation, while dampened IL-7 production is associated with reduced T cell numbers." (PMID 38038708, 2024). "Additionally, the induced level of IL-7 by melatonin enhances the anti-tumor activity of CD8+ T-cells in HCC patients and has been suggested to be a therapeutic candidate for HCC treatment." (PMID 36651944, 2023). "The effects of IL7 seemed to dominate, although IL7 and Flt3L increased DCs in the tumor." (PMID 37754534, 2023). "In addition, treatment of the primary tumor with IL-7–CBD and CBD–IL-12 exhibited notable benefits when compared to the CBD–IL-12 monotherapy in long-term anticancer immune response." (PMID 38019919, 2023). "IL-2, IL-15, and IL-21 in the IL-2 cytokine family play a positive role in anti-tumor effects, and IL-4, IL-7 and IL-9 possess pleiotropic functions, with diverse roles in cancer immunity as they can have pro-tumorigenic functions as well as anti-tumorigenic characteristics." (PMID 36936961, 2023). "Furthermore, IL‐7 can repair T‐cell injury in cancer patients and overcome an immunosuppressive tumor microenvironment." (PMID 36583472, 2023). "Gene expression analysis of the tumor lesions for selected immune-related genes, confirmed a clear induction of markers associated with T cell activation and recruitment in SD101-treated mice (Perforin, Icos, Cd38, Ifng, Il2ra, Il7 and Cxcl10)." (PMID 37365634, 2023). "Similarly, the functional relevance and mechanisms of XIST in inhibiting tumor suppressive cytokine/chemokines (i.e., IL-7, IL-15, and IL-18) need to be determined." (PMID 36922677, 2023). "Mutations in IL-7R in our primary tumor and lung metastasis may represent impaired IL-7 signaling in the tumor immune response." (PMID 39086683, 2023). "Furthermore, Ad-REIC exhibited anti-tumor activity at distant tumor sites via effects on IL-7, which promotes natural killer (NK) cell infiltration." (PMID 36497305, 2022). "For this reason, IL-7 could selectively promote anti-tumor responses of T cells, while immunosuppressive activities of Treg cells, if not decreased, remained intact." (PMID 36419058, 2022). "In addition, the correlation between the IL-7 serum level and the histopathological characteristics of the tumor has been evaluated." (PMID 35794603, 2022). "We armored 28z CAR-T cells (CD28 co-stimulator) with IL-7 to enhance cell proliferation and effector functions, which could improve tumor cell elimination." (PMID 35869100, 2022). "Subsequently, cytokine secreted from T cells in response to those tumor cells was increased, and those cytokines including IL‐2, IL‐7, IL‐15, and interferon gamma (IFN‐g), could induce PD‐L1 expression." (PMID 34907653, 2022). "Moreover, several publications have described an autocrine action of the IL‐7/IL‐7R pathway on tumor cells to promote cell proliferation." (PMID 36054746, 2022). "Secondly, the two techniques measure IL‐7 expression in two different manners, whereas RNASeq measures the number of IL‐7 mRNA copies present in the tumor at a single time point, the time of biopsy, IL‐7 levels in PE result from the accumulation over time of this cytokine in the PE." (PMID 36054746, 2022). "Adjuvant IL-7 also contributed to the prolonged survival of activated T cells, enhanced effector responses, and increased production of cytokines, which boost vaccine-elicited immunity and survival in tumor-bearing mice." (PMID 36389666, 2022).
tumor (continued). "IL-7 is a vital cytokine that affects the survival of tumor-infiltrating T cells." (PMID 36142322, 2022). "In addition, the combination of these two cytokines did not increase the number of percentage of exhausted CD8+ T cells, while IL-7 played a more important role in maintaining T cells in the tumor microenvironment." (PMID 36142322, 2022). "In tumor models that were unresponsive to ICIs combined with anti-PD-1 antibodies or anti-CTLA4 antibodies alone, it was further confirmed that intratumoral injection of an oncolytic bovine poxvirus encoding IL-7 and IL-12 combined with ICI therapy improved anti-tumor activity." (PMID 35833121, 2022). "Noteworthy, we assessed the mice organ in the mice treated with 28z /IL-7 CAR-T cells on day 32 after tumor cell injection, CD3 + T cells were the major human cells detected in peripheral blood, bone marrow and spleen, supporting the notion that IL-7 promotes CAR-T cell persistence in vivo." (PMID 35869100, 2022). "Moreover, the survival of tumor‐bearing mice was modestly improved in Il7−/− recipient mice compared with the control Il7+/− and Il7−/− recipient mice." (PMID 35156727, 2022). "Moreover, both 28z and 28z/IL-7 CAR-T cells displayed similar cytokine expression profiles in the presence of tumor cells, which differed from cytokine profiles of resting CAR-T cells." (PMID 35869100, 2022). "Furthermore, T cell memory elicited by cancer vaccines and IL-7 protected tumor-free mice model from a second tumor challenge." (PMID 36389666, 2022). "On the other hand, evidence shows that IL-7 can be produced by the stroma of tumor cells." (PMID 35794603, 2022). "It has been postulated that IL-7/IL-7R signaling may promote tumor growth by two separate signaling pathways, angiogenesis and the upregulation of Tregs, thereby decreasing cytotoxic T-cell activity." (PMID 36139575, 2022). "In addition to its role in T-ALL formation, IL-7 also affects the invasion and growth of other tumor cells." (PMID 36142322, 2022). "IL-7/IL-7R have dual roles in the development of cancer, and exploring the IL-7R-mediated signaling pathways has shown good therapeutic effects in both liquid tumors and some solid tumor models, indicating a promising future for inhibiting tumor occurrence." (PMID 36142322, 2022). "Thus, we concluded that 28z/IL-7-CAR T cells acquired effector T cell functions by downregulating OPA-1 for eliminating tumor cells." (PMID 35869100, 2022). "Eliminating lymphocytes in the tumor microenvironment facilitates infused cells’ trafficking to the tumor site and their accessibility to various homeostatic cytokines, including IL-2, IL-7, and IL-15, while also reducing immunosuppressive cells that impair antigen-presentation." (PMID 35515137, 2022). "Intriguingly, the cytotoxicity of peripheral blood lymphocytes of patients elevated significantly during treatment, demonstrating that the IL-7-expressing tumor cell vaccine was immunological and capable to stimulate a robust immune response against metastatic cancers." (PMID 36389666, 2022). "In addition to the induction of IL-7 secretion, Ad-REIC facilitates an anti-tumorigenic microenvironment by promoting tumor-associated antigen-specific CD8+ cytotoxic T lymphocytes (CTLs)." (PMID 36497305, 2022). "Furthermore, KEGG pathway enrichment analyses showed their significant enrichment in the IL-7 signaling pathway, which is involved in tumor migration and invasion, such as the NF-κB pathway and MAPK pathway in HNSCC cell lines." (PMID 35690612, 2022). "Furthermore, tumor-derived IL-7 controls the accumulation and activity of both protumoral γδT17 and iNKT17 cells in breast and ovarian cancer models." (PMID 34298791, 2021). "On the other hand, IL-7/IL-7R improves chemotherapeutic sensitivity and anti-tumor immunity." (PMID 35069695, 2021). "Additionally, IL7-Fc further enhanced anti-tumor responses that were induced by recombinant human IL2 in the same mouse model." (PMID 34440787, 2021).
tumor (continued). "In addition, a pre-clinical study comparing CAR T cells secreting different γ-chain-cytokines (IL-2, IL-7, IL-15, and IL-21) found increased anti-tumor activity with all the cytokines tested, but effects were mediated through different mechanisms." (PMID 33746981, 2021). "However, recent preclinical studies have shown that other gamma-chain cytokines (such as IL-7 and IL-15) promote a less-differentiated T cell phenotype, resulting in longer persistence and better anti-tumor effects in comparison to IL-2." (PMID 34503109, 2021). "Others have reported superior tumor control by IL-7/IL-15 than IL-2–expanded T cells." (PMID 33156338, 2021). "T-cell stimulatory common γ chain cytokines IL-7, IL-15, or IL-21 are capable of supporting the generation of memory cells with improved mitochondrial fitness and less overt T-cell differentiation compared to the use of IL-2, improving anti-tumour immunity." (PMID 34960140, 2021). "Alteration of IL7 signalling was common in iAMP21 tumours suggesting that JAK2 inhibitors may have utility in this group." (PMID 34753926, 2021). "Further, IL7-Fc decreased the proliferation of adoptively transferred and immune-activated tumor-reactive CD8+ T cells in immunocompetent mice by inducing the massive expansion of endogenous T cells, thereby limiting the space for adoptively transferred T cells." (PMID 34440787, 2021). "Besides, IL-7 exerts significant effects on anti-virus and anti-tumor activities, as demonstrated multiple times in vitro and in vivo." (PMID 34956167, 2021). "Therefore, IL-7 and IL-15 can be potential alternatives to using IL-2 in the generation of tumor specific T cells." (PMID 34012451, 2021). "Furthermore, mice treated with CD3+CD34+ cells transduced following IL-7 culture had lower tumor volumes when compared to those treated with activated CD3+CD34+ cells (p = 0.0480)." (PMID 34172810, 2021). "Subsequently, transfection of tumor cells with genes coding for cytokines that promote antigen presentation (discussed later), activate T cells and APC or induce costimulatory molecules (IFNγ, IL-2, IL-4, IL-7, GM-CSF) were shown to increase tumor immunogenicity and elicit antitumor immunity." (PMID 33671123, 2021). "However, in RT-qPCR the significance of both CD40LG and IL-7 was observed only before last fraction among all the tumour types." (PMID 33941218, 2021). "IL-7 regulates tumor proliferation, apoptosis, and tumor lymphangiogenesis." (PMID 33981850, 2021). "In addition, ARI2h cells expanded with IL-2, IL-15, or IL-15/IL-7 were injected into MM tumor-bearing mice to assess their in vivo efficacy." (PMID 34298748, 2021). "MMP-3 and MMP-7 drive the IL-7-induced tumor progression, migration, and invasion of DU-145 cells." (PMID 34768524, 2021). "Similarly, intratumoral delivery of IL-12 in combination with IL-7, by a tumor-selective oncolytic vaccinia virus, culminated in tumor rejection and increased multiple antitumor immune pathways." (PMID 33777008, 2021). "Therefore, a single subcutaneous injection of OVA-NPs-IL-7 into animals provoked tumor-specific and also memory-like immune responses." (PMID 34835555, 2021). "In addition, previous reports have shown the long-term benefits of IL-7 therapy on the anti-tumor efficacy of Ag-specific effector CD8+ T cells." (PMID 34445415, 2021). "Preclinical studies have validated the anti-tumor potency of IL-7 therapy." (PMID 34925323, 2021). "In addition, IL-7 can aid the activation of immune cells in anti-virus and anti-tumor immunity and plays important roles in the restoration of immune function." (PMID 34956167, 2021). "Furthermore, when CEA-CAR-T cells were co-inoculated with IL-7- and IL-12-expressing mesenchymal stem cells, tumour inhibition was enhanced, resulting in prolonged survival." (PMID 34769211, 2021).